HLA-DOB (major histocompatibility complex, class II, DO beta)
Description:
Important modulator in the HLA class II restricted antigen presentation pathway by interaction with the HLA-DM molecule in B-cells. Modifies peptide exchange activity of HLA-DM.
Synonyms: DOB; HLA_DOB
Tractability: Antibody: UniProt places it where antibodies can reach, with medium confidence; UniProt predicts a signal peptide or a membrane-spanning region.
Gene: Protein-coding gene on chromosome 6 (32,812,763 to 32,820,466, reverse strand). Ensembl gene ENSG00000241106.
Subcellular location: Endosome membrane; Lysosome membrane
Pathways (Reactome):
Immune System: MHC class II antigen presentation
Gene Ontology:
Molecular function: MHC class II protein complex binding; MHC class II receptor activity; peptide antigen binding
Biological process: negative regulation of antigen processing and presentation of peptide antigen via MHC class II; antigen processing and presentation of exogenous peptide antigen via MHC class II; peptide antigen assembly with MHC class II protein complex; positive regulation of immune response; positive regulation of T cell activation; antigen processing and presentation; immune response
Cellular component: lysosome; MHC class II protein complex; late endosome membrane; lysosomal membrane; endosome membrane; membrane
Genetic constraint (gnomAD): Loss-of-function variants: 22 observed, 25.84 expected, observed/expected ratio (o/e) 0.85, 90% interval 0.61 to 1.22. The upper end of that interval is the gene's LOEUF score, 1.22, which puts it in group 5 of 6, group 1 being the genes least tolerant of losing a copy. Missense variants: 292 observed, 314.74 expected, observed/expected ratio (o/e) 0.93, 90% interval 0.84 to 1.02. Synonymous variants: 132 observed, 123.62 expected, observed/expected ratio (o/e) 1.07, 90% interval 0.93 to 1.23.
Homologues: Orthologues: chimpanzee PATR-DOB (99% identical), rabbit HLA-DOB (78% identical), guinea pig HLA-DOB (75% identical), pig HLA-DOB (75% identical), mouse H2-Ob (75% identical), rat RT1-DOb (71% identical). Paralogues in human: HLA-DRB1 (54% identical), HLA-DRB5 (53% identical), HLA-DQB1 (53% identical), HLA-DQB2 (53% identical), HLA-DPB1 (51% identical), HLA-DQA2 (21% identical), HLA-DQA1 (19% identical), HLA-DOA (19% identical), HLA-DRA (19% identical), HLA-DMB (18% identical), HLA-DPA1 (18% identical), HLA-DMA (16% identical), and 1 more.
Diseases named in the same sentence as HLA-DOB in open-access papers:
HLA-DOB is named in the same sentence as 36 diseases in open-access papers, as found by Europe PMC text mining. Sharing a sentence is not in itself a finding about the gene and the disease. The quoted sentences say what the papers report.
ovarian carcinoma (8 papers, 2019 to 2025). A malignant neoplasm originating from the surface ovarian epithelium. "Similarly, low HLA-DOB expression in ovarian cancer was associated with a poor prognosis." (PMID 40867248, 2025). "Another study also further confirmed through multivariable Cox regression that high levels of HLA-DOB expression can be used as an independent predictor of overall survival in patients with ovarian cancer." (PMID 40861805, 2025). "In addition, Although Wang’s study built a five-gene risk model behaving well in prognostic prediction, the role of some genes, such as UBD, ATP1A3, and HLA-DOB, remains unclear in ovarian cancer." (PMID 37095524, 2023). "For ovarian cancer dataset, the genes CYP2R1 and HLA-DOB detected by the proposed gsslasso method, were also detected by both lasso and cMCP methods." (PMID 30813883, 2019). "Although CD38, BATF2, and HLA-DOB have no statistical significance, they show an increasing trend of expression in ovarian cancer." (PMID 34868310, 2021).
asthma (4 papers, 2020 to 2024). "Interestingly, we also noticed that estrogen-induced the expression of many of the COVID-19 and asthma-related risk genes involving HLA-DRA, HLA-F, and HLA-DOB, which play an important role in the immune response." (PMID 39872660, 2024). "Enriched KEGG pathways could be strongly related to inflammatory processes and regulation in the mixed-cell analysis (with TNF and the HLA, human leukocyte antigen, loci HLA-DRA and HLA-DOB largely contributing to this finding), including the KEGG pathway “Asthma”." (PMID 33076907, 2020).
COVID-19 (4 papers, 2021 to 2024). A disease caused by infection with severe acute respiratory syndrome coronavirus 2. "The HLA-DOB missense variant rs2071554/T is underrepresented in the COVID-19[-] compared to COVID-19[+] (p = 0.0039, OR = 7.3) and the general population (p = 0.0037)." (PMID 34650566, 2021). "Finally, variant rs2071554 from HLA-DOB seems to be overrepresented only among COVID-19[+] women." (PMID 34650566, 2021). "Protein-protein interaction analysis of the effects exerted by anti-COVID-19 vaccination revealed one cluster comprised mainly of various HLA types, i.e., HLA-DOB, HLA-F, HLA-G, and ISG20." (PMID 39744634, 2024). "Furthermore, we found that the genes mediated by high levels of estrogen highly overlapped with the risk genes for COVID-19 and asthma diseases, involving HLA-DRA, HLA-F, and HLA-DOB." (PMID 39872660, 2024).
multiple myeloma (4 papers, 2017 to 2022). "The expression of HLA-DOB in multiple myeloma was significantly higher than that in normal plasma cells, suggesting that it was a potential target for immunotherapy." (PMID 35812403, 2022). "The expression of HLA-DOB in multiple myeloma is significantly higher than that in normal plasma cells, suggesting that it is a potential target for immunotherapy." (PMID 34868310, 2021). "HLA-DOB, a B-cell lineage, MHC-II-related molecule has been reported to have strong immunogenicity for human T-cells, one of its identified CTL epitopes HLA-DOB232–240 acts as a resilient immunotherapeutic candidate for targeting multiple myeloma." (PMID 28210261, 2017).
periodontitis (3 papers, 2020 to 2021). An acute or chronic inflammatory process that affects the tissues that surround and support the teeth. "The strong associations among ISG20, ESRP1 and activated B cell, BCR signaling pathway, and HLA-DOB in periodontitis were first identified in our study." (PMID 34285922, 2021). "Four common crosstalk genes between periodontitis and DS were acquired, i.e., CD19, FCRL5, FCRLA, and HLA-DOB, of which the latter had the highest prediction accuracy." (PMID 34545294, 2021). "Our study depicted the correlations among RBPs and immune microenvironment and biological reactions in periodontitis, with strong correlations of the RBPs ISG20 and ESRP1 with activated B cell infiltration, BCR signaling activation, and HLA-DOB expression." (PMID 34285922, 2021). "Correlation analysis revealed HLA-DOB and ISG20 as the most positively correlated HLA-RBP pair, with higher activities of both in periodontitis." (PMID 34285922, 2021).
Autoimmunity (2 papers, 2021 to 2024). The occurrence of an immune reaction against the organism's own cells or tissues. "HLA-DOB has been demonstrated to be related to autoimmunity in celiac disease and ankylosing spondylitis." (PMID 34545294, 2021).
lupus (2 papers, 2020 to 2023). "The lupus epistasis network also contains a significant interaction between HLA-DOB and PBX2, which are both located within the MHC class II region on chromosome 6." (PMID 32774345, 2020).
viral infections (2 papers, 2024). "The human leukocyte antigen HLA-DOB plays an important role in viral infections by influencing multiple alleles involved in antigen presentation." (PMID 38938570, 2024). "Previous researches have indicated that human leukocyte antigen HLA-DOB, which can influence several alleles involved in antigen presentation, plays a crucial role in viral infections." (PMID 37855981, 2024).
cervical cancer (1 paper, 2021). A primary or metastatic malignant neoplasm involving the cervix. "Among those, both HLA-DOB and RP11-384K6.2 display associations with cervical cancer in three tissues; 80.0% (16/20) are located in the MHC region (Chr 6: 25,000,000-34,000,000) and 70.0% (14/20) are protein coding genes." (PMID 33403041, 2021).
cutaneous melanoma (1 paper, 2025). A primary melanoma arising from atypical melanocytes in the skin. "HLA-DOB was the only risk gene of psoriasis that showed differential expression in cutaneous melanoma based on transcriptional analysis." (PMID 40861805, 2025). "Importantly, we also found that HLA-DOB can be served as a key “coordinator” between cutaneous melanoma and psoriasis: a risk gene of psoriasis and a protective factor of cutaneous melanoma." (PMID 40861805, 2025).
melanoma (1 paper, 2025). A malignant, usually aggressive tumor composed of atypical, neoplastic melanocytes. "HLA-DOB was downregulated in melanoma and associated with better prognosis (P=0.033)." (PMID 40861805, 2025).
multiple sclerosis (1 paper, 2024). A progressive autoimmune disorder affecting the central nervous system resulting in demyelination. "HLA-DOB also shows the most prominent differences in gene expression between multiple sclerosis patients and healthy controls." (PMID 39610928, 2024).
psoriasis (1 paper, 2025). An autoimmune condition characterized by red, well-delineated plaques with silvery scales that are usually on the extensor surfaces and scalp. "The co-localization analysis revealed genes positively associated with the risk of psoriasis, including HLA-DOB, NOTCH4, and VARS2." (PMID 40861805, 2025).
vitiligo (1 paper, 2025). Generalized well circumscribed patches of leukoderma that are generally distributed over symmetric body locations and is due to autoimmune destruction of melanocytes. "Finally, we obtained ten matched genes (GP1BA, ANKS4B, CCDC87, CA8, HLA‐DOB, RHEBL1, NLRP7, GZMH, HERPUD1, and MAP2K1) as a vitiligo‐gene signature (VGS)." (PMID 40974370, 2025).
tumor (10 papers, 2019 to 2025). "The downregulation of HLA-DQA1, HLA-DOB, and ITM2A, which are associated with immune evasion and tumor progression, is consistent with the immune-excluded phenotype observed in the mesenchymal-like (C5) and aggressive basal/squamous-like (C4) subtypes." (PMID 40867248, 2025). "At present, there are few studies on the involvement of HLA-DOB in tumor mechanisms." (PMID 35812403, 2022). "Furthermore, the very high numerical level of normalized expression of all these genes, except for HLA-DOB, are likely indicative of expression by the actual adenocarcinoma cells within the tumor." (PMID 32901107, 2020). "Furthermore, these genes are also expressed at very high levels, with the exception of HLA-DOB, that are indicative of being expressed by epithelial cells within the actual tumor." (PMID 31394808, 2019). "We used the TIMER database to analyze the differential expressions of CD38, ACE2, BATF2, HLA-DOB, and WARS between various tumor tissues and normal tissues." (PMID 34868310, 2021). "Tumor samples with a positive HPV status expressed significantly higher levels of all of the B cell-related genes analyzed, namely, BLK, CD19, CR2, HLA-DOB, MS4A1 and TNFRSF17." (PMID 31623665, 2019). "Transcriptome analysis showed that HLA-DOB has a potential role in SKCM suppression and was significantly positively correlated with overall survival, which may be related to the anti-tumor immune response." (PMID 40861805, 2025).
cancer (5 papers, 2017 to 2025). A tumor composed of atypical neoplastic, often pleomorphic cells that invade other tissues. "An intestinal immune network for IgA production might provide new markers in enteric DLBCL, such as CCR10, TNFRSF13B, AICDA, and HLA-DOB, as well as genes involved in transcriptional misregulation in cancer (NFKBIZ, FUT8, LMO2, CCND2, BCL2A1, ETV6, and CDK14)." (PMID 29992138, 2018). "When it comes to the HLA-DOB, the role of HLA-DOB in cancers remains uncertain." (PMID 40861805, 2025).
infection (2 papers, 2014 to 2021). The state of being infected such as from the introduction of a foreign agent such as serum, vaccine, antigenic substance or organism. "For instance, the OR for MICB*004 and HLA-DOB*01:02 for symptomatic infection is 2.8 and 7.39, respectively." (PMID 34650566, 2021). "The results indicated that HLA-DMA rs1063478 and HLA-DOA rs2284191 were independent factor of being anti-HCV positive, while HLA-DOB rs7383287 and LMP2 rs17587 were independent factor of infection chronicity." (PMID 25528575, 2014). "HLA-DOB rs7383287 and LMP2 rs17587 were independent factors of infection chronicity." (PMID 25528575, 2014).
neurological disorders (1 paper, 2022). "Interestingly, several genes encoded in the HLA locus, which has been implicated in SCZ and other psychiatric and neurological disorders, were picked up by our inference downstream of the identified transcription factors (HLA-DOA, HLA-DOB, HLA-DRB1, HLA-DMA, and BRD2)." (PMID 36344995, 2022).
HLA-DOB also shares sentences with these, for which no sentence is quoted: rheumatoid arthritis (3 papers); celiac disease (2); schizophrenia (2); Sepsis (2); adenocarcinoma (1); ankylosing spondylitis (1); breast carcinoma (1); cervix tumors (1); chickenpox (1); chronic hepatitis B (1); chronic lymphocytic leukemia (1); clear renal cell carcinoma (1); graft versus host disease (1); Kawasaki disease (1); lymphoma (1); non-small cell lung carcinoma (1); psoriatic arthritis (1); type I diabetes (1).